LINC01877 (long independently transcribed non-coding RNA 1877)
Gene: Long non-coding RNA gene on chromosome 2 (199,608,062 to 199,750,341, forward strand). Ensembl gene ENSG00000238217.
Diseases named in the same sentence as LINC01877 in open-access papers:
LINC01877 is named in the same sentence as 1 disease in open-access papers, as found by Europe PMC text mining. Sharing a sentence is not in itself a finding about the gene and the disease. The quoted sentences say what the papers report.
Cluster headache (2 papers, 2022 to 2025). A type of headache characterized by repeated attacks of unilateral pain lasting 15 to 180 minutes and associated with local autonomic signs. "The four cluster headache susceptibility loci that were identified by this GWAS were rs113658130 near LINC01877/SATB2 (SATB homeobox 2), rs4519530 in MERTK, rs12121134 near LINC01705/DUSP10 (Dual Specificity Phosphatase 10), and rs11153082 in FHL5." (PMID 39560176, 2025). "Moreover, we found evidence of suggestive association among previously suggested loci to be involved in cluster headache, including LINC01877, LINC01705, ADCYAP1R1, and MME." (PMID 36404298, 2022).